CR2 (complement C3d receptor 2)
Diseases named in the same sentence as CR2 in open-access papers (continued):
Sharing a sentence is not in itself a finding about the gene and the disease.
Stroke (3 papers, 2015 to 2021). Sudden impairment of blood flow to a part of the brain due to occlusion or rupture of an artery to the brain. "This conclusion is supported by data showing that CR2-Crry more completely blocks complement activation than CR2-fH, as determined by comparing post-stroke brain levels of the complement activation product, C5a." (PMID 26714866, 2015). "C3a and C5a have neuroprotective/regenerative roles, and whereas CR2-fH treatment significantly inhibited C5a generation in the ipsilateral brain for up to 3 days after stroke, C5a levels were still significantly higher than in brains from CR2-Crry-treated mice." (PMID 26714866, 2015). "C3 deficiency and site-targeted complement inhibition with either CR2-Crry (inhibits all pathways) or CR2-fH (inhibits alternative pathway) significantly reduced infarct size, reduced apoptotic cell death, and improved neurological deficit score in the acute phase after stroke." (PMID 26714866, 2015). "In addition to maintaining post-stroke neurogenesis, CR2-fH treatment also promoted significantly more neuroblast migration from the SVG compared to wt mice, findings that correlated with improved performance on spatial learning and passive avoidance tasks in the subacute phase after stroke." (PMID 26714866, 2015). "The concept of CR2-fH providing optimal longer-term protection by self-limited complement activation is further supported by findings that high-dose, but not low-dose, C3aR antagonism impaired post-stroke SVZ neurogenesis in the subacute phase." (PMID 26714866, 2015). "For this study, we utilize CR2-fH, an inhibitor shown to specifically inhibit the alternative pathway, and CR2-Crry, an inhibitor of all complement pathways that has been shown to provide acute protection after stroke, but that has not been investigated with regard to subacute outcome." (PMID 26714866, 2015).
Alzheimer disease (2 papers, 2013 to 2020). A progressive, neurodegenerative disease characterized by loss of function and death of nerve cells in several areas of the brain leading to loss of cognitive function such as memory and language. "This network contains the proinflammatory cytokine Il1a, previously associated with Alzheimer’s disease, development and plasticity, immune associated genes (Cd80, Cr2, Cd27, Dapp1) and chemokines (Ccl3, Ccl4, Ccl21)." (PMID 23742273, 2013).
Crohn disease (2 papers, 2019 to 2022). A gastrointestinal disorder characterized by chronic inflammation involving all layers of the intestinal wall, noncaseating granulomas affecting the intestinal wall and regional lymph nodes, and transmural fibrosis. "Similarly, patients with Crohn’s disease show remission when the frequencies of intestinal IgM and CR2/CD21 positive B cells were increased." (PMID 31683524, 2019).
dengue (2 papers, 2018 to 2023). "The levels of CR1 and CR2 were modulated during the clinical course of dengue fever, with the reduction in CR2 levels associated with disease severity and with previous or current DENV infections." (PMID 37833411, 2023). "This present study aims to investigate the potential associations of CR1, CR2 polymorphisms, and plasma CR1 and CR2 protein levels with the severity of dengue fever in Vietnamese patients." (PMID 37833411, 2023). "This study investigated the possible association of genetic polymorphisms and plasma levels of CR1 and CR2 with dengue disease." (PMID 37833411, 2023). "In conclusion, the current study revealed that the CR1 rs6691117A/G and CR2 rs1048971G/A SNPs are associated with a progression to the severity of dengue fever." (PMID 37833411, 2023). "The current study is the first to show an association between the CR1 rs6691117A/G and CR2 rs1048971G/A SNPs and the progression to severe dengue fever." (PMID 37833411, 2023). "Similarly, our results suggest that the CR2 SNP rs1048971G/A is associated with an increased risk of progressing to severe dengue." (PMID 37833411, 2023). "Although this study represents the first attempt to elucidate the involvement of CR1 and CR2 in the progression of dengue fever, several limitations must be acknowledged." (PMID 37833411, 2023). "We analyzed the correlation of the plasma CR1 and CR2 levels with several laboratory parameters in both healthy controls and dengue patients." (PMID 37833411, 2023). "Regarding the CR2 protein, we also observed that CR2 levels were significantly decreased in all dengue patient groups when compared to healthy controls (P < 0.0001)." (PMID 37833411, 2023). "Within the dengue patient groups, the CR2 protein levels were lowest in severe dengue patients, followed by patients with DWS and dengue fever patients (P < 0.001)." (PMID 37833411, 2023). "Plasma CR1 and CR2 levels were decreased in dengue patients compared to healthy controls (P < 0.0001) and were associated with platelet counts." (PMID 37833411, 2023). "The results revealed that CR2 levels were decreased in dengue patients positive for anti-DENV specific IgG and IgM and internal/mucosal bleeding (P = 0.032, 0.016, and 0.011, respectively)." (PMID 37833411, 2023). "In conclusion, this study revealed a reduction in CR2 levels in dengue patients and that the CR1 SNP rs6691117A/G is associated with the dengue severity." (PMID 37833411, 2023). "At present, the pathogenesis of dengue virus infection remains incompletely understood, particularly the role of CR1 and CR2 proteins, along with CR1 and CR2 polymorphisms, in dengue disease has yet to be investigated." (PMID 37833411, 2023). "However, we did not observe any significant difference in CR2 levels among different genotypes and haplotypes of CR2 SNPs in dengue patients." (PMID 37833411, 2023). "In addition, we also analyzed the correlation between CR1 and CR2 levels in healthy controls and dengue patients." (PMID 37833411, 2023). "Our findings indicate that CR2 levels decrease as dengue fever progresses through different stages." (PMID 37833411, 2023). "The correlation of CR2 levels with platelet counts suggests that CR2 could be an additional biomarker for the prognosis of severe dengue disease." (PMID 37833411, 2023). "Further studies are warranted to elucidate the roles of CR1 and CR2 in the immune response against DENV infection and the progression of dengue fever." (PMID 37833411, 2023). "Our results contribute to a deeper understanding of the roles of CR1 and CR2 during the immune response against DENV infection and the pathogenesis of dengue fever." (PMID 37833411, 2023). "Consequently, further studies are necessary to elucidate the functional roles of CR1 and CR2 in DENV infection and the clinical progression to severe dengue." (PMID 37833411, 2023).
dengue (continued). "In addition, CR2 levels were positively correlated with platelet count but inversely correlated with liver enzymes AST and ALT levels, further emphasizing CR2's role in responding to DENV infection and the progression of dengue fever." (PMID 37833411, 2023). "Although CR1 and CR2 have been associated with infections with several viruses such as HIV, HBV, and SARS-CoV-217–19, their roles in the immune response to DENV infection and the progression of dengue fever have not been investigated, so far." (PMID 37833411, 2023).
glaucoma (2 papers, 2020 to 2021). Increased pressure in the eyeball due to obstruction of the outflow of aqueous humor. "AAV-mediated expression of soluble C3d-targeted CR2-Crry by retinal ganglion cells reduces neuronal loss in a glaucoma model, in part by inhibiting phagocytosis of opsonized RGC synapses." (PMID 33072106, 2020). "Complement C3 activation intersects the three pathways of complement activation, and one group assessed an AAV vector encoding a C3 inhibitor, CR2-Crry (AAV2-CR2-Crry), in the DBA/2J mouse model of glaucoma." (PMID 33920974, 2021). "AAV-mediated intravitreal delivery of a CR2-Crry construct, which inhibits all complement pathways at C3 activation, provides neuroprotection to RGCs in murine models of glaucoma and MS." (PMID 33072106, 2020).
ischemia (2 papers, 2015 to 2021). A hypoperfusion of the BLOOD through an organ or tissue caused by a PATHOLOGIC CONSTRICTION or obstruction of its BLOOD VESSELS, or an absence of BLOOD CIRCULATION. "While it is possible that alternative pathway inhibition with CR2-fH may promote post-ischemia neurogenesis by increasing VEGF levels, it does not appear to have any effect on angiogenesis in the subacute phase." (PMID 26714866, 2015).
prion disease (2 papers, 2011 to 2017). A transmissible disease that is caused by a protein that is able to induce abnormal folding of normal cellular proteins, leading to characteristic spongiform brain changes, which are associated with neuronal loss without an inflammatory response. "In mouse models, genetic depletion of Cr2 causes either a delay or complete prevention of prion disease, but the relative importance of CD35 versus CD21 in promoting prion disease remains unknown." (PMID 29202042, 2017).
prostate carcinoma (2 papers, 2010 to 2018). A carcinoma that arises from epithelial cells of the prostate gland. "In transgenic mouse models of prostate cancer, NE-10 prostate tumor from subcutaneous transplantation of 12T-10 tumor and CR2-TAg prostate, Notch-Hes1 signaling is down-regulated and may be responsible for the promotion of the neuroendocrine differentiation of prostate cancer cells." (PMID 21106062, 2010).
schizophrenia (2 papers, 2017 to 2025). A major psychotic disorder characterized by abnormalities in the perception or expression of reality. "Its second protein, CR2, is part of the complement system, which is implicated in schizophrenia." (PMID 39911945, 2025).
T-cell leukemia (2 papers, 2017 to 2023). A malignant disease of the T-lymphocytes in the bone marrow, thymus, and/or blood. "Evidence for a CR2 and CR1 function in T cells was their 3- to 10-fold enhancement of C3-dependent HIV infection in the HPB-ALL T cell leukemia cell line." (PMID 28814669, 2017).
cerebral artery occlusion (1 paper, 2019). "Both CR2-Crry (an inhibitor of all complement pathways) and CR2-fH (an inhibitor of the alternative pathway) significantly reduced infarct size, apoptotic cell death, and neurological deficits in a mouse model of transient middle cerebral artery occlusion (tMCAO)." (PMID 31281252, 2019).
cholangiocarcinoma (1 paper, 2024). A carcinoma that arises from the intrahepatic biliary tree (intrahepatic cholangiocarcinoma) or from the junction, or adjacent to the junction, of the right and left hepatic ducts (hilar cholangiocarcinoma). "For instance, the adhesive receptor CR2 for Herpesviridae displayed an upregulation of over 400 times in cholangiocarcinoma (CHOL), while the receptor MOG for the Rubella virus showed an upregulation of over 300 times in kidney chromophobe (KICH) cancer." (PMID 38785923, 2024).
choroidal (1 paper, 2025). "In another choroidal neovascularization (CNV) study, antibody blocking of the alternative complement pathway with the fusion protein CR2-fH, combining the iC3b/C3d-binding region of CR2 and the N-terminus of the regulatory CFH, normalized anaphylatoxin levels, and reduced lesion size." (PMID 39775695, 2025).
Cognitive impairment (1 paper, 2025). Abnormal cognition is characterized by deficits in thinking, reasoning, or remembering. "We observed a reduced proportion of synapses engulfed by microglia in CR2-Crry-treated mice compared with vehicle-treated mice, supporting our hypothesis that cognitive impairment in vehicle-treated mice is driven, at least in part, by complement-mediated phagocytosis." (PMID 41261092, 2025).
complement deficiency (1 paper, 2025). A genetic deficiency of any of the component of the complement system (including the classical, alternative, and terminal pathway components), that can either be acquired or inherited. "Therapeutic use of CR2-fH fusion proteins mimicked complement deficiency protection, reinforcing MAC’s involvement in inflammatory joint disease." (PMID 41550949, 2025).
diabetic nephropathy (1 paper, 2023). "In diabetic nephropathy, we identified positive correlations specifically with complement components C2 and C5 and receptors C5AR2 and CR2." (PMID 38069385, 2023).
Encephalopathy (1 paper, 2023). Encephalopathy is a term that means brain disease, damage, or malfunction. "Similar to the results of our data, Millichap and colleagues report a similar clustering of case variant propensity solely in the pore region and CR2 for mutations of KCNQ2 associated with encephalopathy." (PMID 37897496, 2023).
Epstein-Barr virus infection (1 paper, 2014). An infection that is caused by Epstein-Barr virus. "The CR2 expressed on astrocytes was shown to be functional, as demonstrated by Epstein-Barr virus infection through the CR2 expressed in human astrocyte cell lines." (PMID 24885042, 2014).
erythroleukemia (1 paper, 2016). Acute erythroid leukemia characterised by the presence of at least 50% erythroid precursors and at least 20% myeloblasts in the bone marrow. "Previously, it was reported that the minor C allele of rs3813946, located in 5′UTR of CR2, reduced transcription of reporter genes in CR2-nonexpressing erythroleukemia cells and CR2 expressing B cells." (PMID 27446959, 2016).
Granuloma (1 paper, 2017). A compact, organized collection of mature mononuclear phagocytes, which may be but is not necessarily accompanied by accessory features such as necrosis. "However, C3d positive T-cells are found in and around granulomas in skin lesions, suggesting a possible role for C3d in co-stimulation by binding CR2 on T-cells resulting in an enhanced immune response." (PMID 28505186, 2017).
Hepatic steatosis (1 paper, 2019). Steatosis is a term used to denote lipid accumulation within hepatocytes. "CR2-Crry inhibits C3 convertase and thus suppresses C3 cleavage and activation, leading to a reduction in both inflammatory cytokine levels and hepatic steatosis after ethanol feeding." (PMID 31076642, 2019).
latent infection (1 paper, 2015). "Interactions between EBVgp350/220 and complement receptor type 2 (CR2)/CD21 and/or (CR1)/CD35 on B-cells is required for cellular attachment and initiation of latent infection." (PMID 25885535, 2015).
metastatic cancer (1 paper, 2021). A carcinoma which has spread from the original site of growth to another anatomic site. "Another elegant study showed that an engineering antibody composed by CR2 (CD21) and Fc region of IgG1 binds C3d deposits on tumor cells and enhanced CDC activation via the Fc portion, and mediates the recognization and recruitment of effector immune cells to metastatic cancer cells." (PMID 34572075, 2021).
myocardial infarction (1 paper, 2018). Gross necrosis of the myocardium, as a result of interruption of the blood supply to the area, as in coronary thrombosis. "Notably, Raldh2 CR2 and Wt1 CR14 enhancers are also activated in adult mouse hearts in response to myocardial infarction (MI), suggesting that embryonic epicardial enhancers are reactivated to repurpose the developmental gene program in adult hearts after injury." (PMID 30583498, 2018).
Noonan syndrome (1 paper, 2016). Noonan Syndrome (NS) is characterized by short stature, typical facial dysmorphism and congenital heart defects. "In any case, the cancer-associated mutations of the 14-3-3 binding motif surrounding S365 represent an interesting parallel to the Noonan-Syndrome associated RAF1 mutations, affecting the equivalent motif around S259 in Raf-1, and the cancer-associated mutations in the CR2 of A-Raf." (PMID 27034005, 2016).
oral cancer (1 paper, 2022). "Lobophorin CR1, CR2, and CR3 showed human oral cancer cell growth inhibition." (PMID 35572656, 2022).
Parkinson’s (1 paper, 2019). "According to the DAVID database, the complement C3d receptor 2 gene, CR2, has been also found in association with Parkinson’s and other neurological disorders." (PMID 31784692, 2019).
preeclampsia (1 paper, 2025). Preeclampsia is a hypertensive disorder of pregnancy that is characterized by new-onset hypertension with proteinuria presenting after 20 weeks of gestation, and depending on mild or severe forms may initially present with severe headache, visual disturbances, and hyperreflexia. "Preclinical studies, such as C1q-deficient mouse models, reveal impaired placentation and preeclampsia-like features, while models like the BPH mouse demonstrate complement-driven inflammation and fetal loss, mitigated by inhibitors like CR2-Crry." (PMID 40777009, 2025).
RASopathy (1 paper, 2016). Developmental syndromes caused by germline mutations (or in rare cases by somatic mosaicism) in genes that alter the Ras subfamily and mitogen-activated protein kinases that control signal transduction. "Experiments using B-Raf proteins with mutations in the CRD, e.g. the RASopathy associated Q257R substitution, or in the CR2, e.g. S365A, have revealed the critical role of CR1/CR2 for auto-inhibition." (PMID 27034005, 2016).
septic peritonitis (1 paper, 2015). Septic peritonitis is an inflammatory condition of the peritoneum that occurs secondary to microbial contamination. "Complement plays an important role in host defense mechanisms, and our finding here is also in accord with a previous study in which it was shown that C3 deficiency, but not CR2-Crry treatment, increased susceptibility to infection in a model of septic peritonitis." (PMID 26714866, 2015).
thymic tumors (1 paper, 2020). "Compared to IL-8 assay, CD31 detection had much lower diagnostic sensitivity and specificity in distinguishing thymomas from other types of thymic tumors; PTK7 or CR2 assay also showed lower discriminatory ability in thymoma diagnosis, only with AUC level 85% and 84%, respectively." (PMID 32985506, 2020).
tularemia (1 paper, 2025). Tularemia is an infection caused by the bacterium Francisella tularensis. "We showed for the first time that mice deficient in C3aR1 and CR2, but not C3 or C5aR1, were more susceptible to tularemia." (PMID 41406154, 2025).
viral pneumonia (1 paper, 2010). Inflammation of the lung parenchyma that is caused by a viral infection. "CR2 targeting complement inhibitors are expected to be ideal drugs for viral pneumonia." (PMID 20144216, 2010). "Therefore, CR2 targeting complement inhibitor is expected to be an ideal drug for viral pneumonia." (PMID 20144216, 2010).